ALB (albumin)
Diseases named in the same sentence as ALB in open-access papers (continued):
Sharing a sentence is not in itself a finding about the gene and the disease.
diabetes (continued). "In this study, almost all patients with diabetes showed normoalbuminuria and the urinary albumin/creatinine ratio was not changed." (PMID 28596160, 2017). "In the multivariable cause-specific method—accounting for non-sudden CV deaths and non-cardiovascular deaths—predictors of SCD in AF after backwards elimination included higher age, increased BMI, CHD, hypertension, diabetes, current smoker, LVH, increased heart rate, and decreased albumin." (PMID 29117224, 2017). "Among all patients, patients with weight loss greater than 10% in the prior 3 months accounted for 86.5%; without autonomous activity, 87.8%; hypertension, 30.1%; diabetes, 21.2%; albumin less than 35 g/L, 78.2%; hematocrit value less than 37%, 49.4%." (PMID 29108336, 2017). "Urine albumin–to–urine creatinine ratio (ACR) level was also gradient-increased two weeks after STZ injection and peaked at week 8, indicating that kidney injury appeared in early stage of mouse diabetes models." (PMID 29285296, 2017). "Considering all time points, 12-h total drainage, pre-operative weight, extra-cardiac arteriopathy, age, diabetes, CABG surgery, pre-operative cardiomegaly and pre-operative albumin level were independently predictive of C-POMS-defined post-operative morbidity outcome." (PMID 28228937, 2017). "Several potential confounders, such as age, gender, comorbidities (Diabetes Mellitus, CVD etc.), serum albumin, residual glomerular filtration rate (rGFR), and even high sensitive C-reaction protein (hs-CRP) and urea clearance (Kt) normalized to total body water (Kt/ Vurea) were taken into account." (PMID 28207885, 2017). "Serum albumin was statistically higher amongst the cases, while the NSD cohort demonstrated a higher proportion of patients with coronary artery disease, congestive heart failure, peripheral vascular disease and diabetes." (PMID 28764654, 2017). "Patients who started HD but were not referred for vascular surgery were more likely to have diabetes mellitus, lower hemoglobin, albumin and eGFR levels and higher urinary protein/creatinine ratios compared to patients who did not start HD and not referred." (PMID 28095805, 2017). "In subgroup analysis, patients with both OH>1.1L and high circulating Angpt2 level had significantly increased risk for commencing dialysis independent of sex, CKD stages, diabetes and serum albumin and hsCRP levels in adjusted model." (PMID 28333979, 2017). "Many studies on diabetes have found that soluble factors that mediate abnormal GEC-podocyte crosstalk may destroy filtration-barrier integrity and eventually lead to albumin leakage." (PMID 28839221, 2017). "On the other hand, studies in animal models of diabetes and in vitro experiments that have determined the effects of high glucose levels on astrocytes' cultures, as well as the AGE-albumin treatment of aortic endothelial cells, demonstrate that these compounds reduce gap junction communications." (PMID 28685011, 2017). "Nevertheless, more studies on the complex relationship between the endocytic machinery components and diabetes features, such as hyperglycemia, lack of insulin, and albumin overload, are indeed necessary." (PMID 28676554, 2017). "There were no changes in urinary albumin excretion and eGFR, suggesting that low-dose aspirin therapy does not affect albuminuria in patients with diabetes." (PMID 26808136, 2016). "Small short-term intervention studies reported increases in insulin and plasma glucose or glycated albumin in hyperlipidaemic patients without diabetes." (PMID 26577796, 2016). "In experimental diabetes early studies of Baynes and co-workers and others showed that the rate of degradation of albumin was not increased but slightly lower in streptozotocin-induced diabetic rats than in healthy controls." (PMID 27338619, 2016).
diabetes (continued). "However, the association weakened below significance (P = 0.073) after controlling for possible confounders (age, sex, hypertension, diabetes mellitus, atrial fibrillation, hyperlipidemia, CCI, NIHSS, CRP, albumin, and eGFR)." (PMID 27096104, 2016). "Albumin reflects the burden of noncardiac comorbidities, as it is reduced in patients with diabetes mellitus, chronic kidney disease, and severe chronic obstructive pulmonary disease." (PMID 26968521, 2016). "Our data demonstrate that two methionine residues in serum albumin (Met-111 and Met-147) are highly oxidized to methionine sulfoxide in patients with diabetes and renal failure and in healthy smokers versus non-smoker controls." (PMID 27929071, 2016). "The study was undertaken to assess level of serum fructosamine, glycated albumin and glycated β-lipoprotein in type 2 diabetes mellitus patients with and without microvascular complications and to find out their correlation with the complications." (PMID 27896233, 2016). "Glycated β-lipoprotein correlated well with FBS, PP2BS, fructosamine and glycated albumin only in diabetes patients with one or more microvascular complication and not in the other two groups." (PMID 27896233, 2016). "This study aimed to assess level of serum fructosamine, glycated albumin and glycated β-lipoprotein in type 2 diabetes mellitus patients with and without microvascular complications and to find out their correlation with diabetes complications." (PMID 27896233, 2016). "In particular, CKD patients with diabetes had more serious proteinuria and low levels of serum albumin and Mg than those of nondiabetic CKD patients." (PMID 26273297, 2015). "Neither types of diabetes have significant differences in their levels of Triglyceride, cholesterol or albumin between the two groups regardless of having diabetic retinopathy." (PMID 27366736, 2015). "In the univariate analysis, the eGFR slope had a significant positive correlation with albumin and negative correlation with age, diabetes, BMI, UPCR, baseline eGFR, AoAC, and cardiomegaly." (PMID 25695046, 2015). "Consistent with the lack of correlation between straylight and HbA1c in this study, they concluded that reduced CS was not related to glycemic control, duration of diabetes or urinary albumin excretion." (PMID 26464020, 2015). "In this study, we found that age, systolic blood pressure, plasma glucose level, serum cholesterol level, and triglyceride level were higher and serum albumin levels were lower in patients with diabetes than in patients without diabetes." (PMID 25674854, 2015). "The association between HBV infection and all-cause mortality did not significantly differ with regards to diabetes, sex, dialysis vintage, or albumin level." (PMID 26263373, 2015). "A retrospective cohort study reported that the subjects with low serum Mg had higher proteinuria and lower serum albumin levels among CKD patients with or without diabetes." (PMID 26273297, 2015). "Because of the strong interaction of diabetes and albumin, we re-analyzed our data without laboratory findings and found that diabetes and low residual renal function were significant risk factors for death of PD patients." (PMID 26121574, 2015). "If a patient does not have diabetes mellitus, but has hypertension and albumin: creatinine ratio < 30 mg/mmol, antihypertensive treatment should be instituted." (PMID 24955116, 2014). "We feel that the higher albumin level does not reflect higher protein consumption, especially when the calcium levels was significantly increased in the non-diabetes group." (PMID 25546434, 2014). "Serial adjustments for demographics and individual covariates (i.e., hemoglobin, diabetes, cardiovascular disease, albumin, hemoglobin, and phosphate) also did not alter coefficient estimates." (PMID 24502751, 2014).
diabetes (continued). "High albumin excretion was related to left ventricular hypertrophy independent of age, blood pressure, diabetes, race, serum creatinine, or smoking, suggesting parallel cardiac damage and albuminuria." (PMID 24982887, 2014). "These patients were also more likely to have diabetes; hypertension; previous CVD; proteinuria; low baseline kidney function; low levels of hemoglobin, platelets, albumin, HDL cholesterol, and calcium; and high levels of total cholesterol, triglycerides, phosphorus, uric acid, and white blood cells." (PMID 25093403, 2014). "Survivors were significantly younger and less likely to have diabetes than nonsurvivors, and had higher levels of serum albumin on admission." (PMID 25210515, 2014). "The difference in prevalence reported by different studies can be attributed to the differences in population indexes such as race, laboratory techniques for urine albumin measurement, and the differences in the definition of microalbuminuria, IFG, and diabetes mellitus." (PMID 23841037, 2013). "In addition, age, diabetes, preexisting CAD, serum albumin, ferritin, CRP, residual GFR, peritoneal Kt/V urea, nPCR, and %LBM were revealed as predictors of mortality." (PMID 24349396, 2013). "In men, univariate Cox analysis revealed that older age, the presence of diabetes mellitus and previous cardiovascular disease, smoking, high BMI and serum hs-CRP levels, low serum albumin concentrations, and higher SAD (≥24.2 cm) were significant risk factors for all-cause mortality." (PMID 24167560, 2013). "Irrespective of the degree of urine albumin excretion, in all adults with diabetes serum creatinine should be measured at least annually." (PMID 24165454, 2013). "Diabetes, estimated GFR and proteinuria showed borderline significance as predictors of progression, and serum albumin was not independently associated with CKD progression." (PMID 24349550, 2013). "Independent correlates were SBP, uric acid, diabetes, total cholesterol, alanine amino transferase (ALT), Cystatin C and serum albumin (negative association) for overt albuminuria; and SBP, CRP and serum albumin only for microalbuminuria." (PMID 23947772, 2013). "Patients with PAD (n = 30) had longer diabetes duration, higher systolic blood pressure (BP), waist-to-hip ratio, HbA1C test, and urinary albumin excretion (UAE) than patients without PAD." (PMID 24295032, 2013). "Linear IgG immunofluorescence along GBM was demonstrated for each of the 46 patients with staining intensity of 1+~4+ on the scale of 1 to 4, in the absence of fluorescence for albumin or a diagnosis of diabetes." (PMID 23586976, 2013). "In a multi-variate Cox hazard model, older age, male gender, comorbidity of diabetes, higher BUN and lower albumin were significant risk factors of death, which is not inconsistent with our previous results and others." (PMID 27785173, 2012). "The impaired response to hepatitis B vaccine in dialysis patients has been also attributed to male gender, poor nutritional status, mainly low serum albumin concentration, serological positivity for hepatitis C virus (HCV) or human immunodeficiency virus (HIV), and diabetes mellitus." (PMID 23326280, 2012). "Positive correlations were found between DR and duration of diabetes, systolic blood pressure (SBP), diastolic blood pressure, glycated hemoglobin, glycated albumin, 24 hurinary albumin excretion, peripheral atherosclerosis (PA), diabetes nephropathy (DN), diabetic peripheral neuropathy, and anemia." (PMID 22844279, 2012). "Therapy of diabetes with either riociguat or telmisartan alone did not lower urinary albumin excretion (p = 0.067 and p = 0.101, respectively) nor albumine-creatinine ratio (p = 0.171 and p = 0.091, respectively)." (PMID 22900035, 2012). "Similarly, measurement of albumin excretion (ACR) was also only done for approximately half (55.8%, 95% CI [50.6 - 61.0%]) of the patients with diabetes." (PMID 22970753, 2012).
diabetes (continued). "In univariate linear regression analysis, sex and body mass index (BMI) were found to be significantly correlated with serum ALT level, but not with age, presence of diabetes, and bilirubin, albumin, cholesterol, and HBV DNA levels." (PMID 22087160, 2011). "Furthermore, systolic pressure, adiponectin, proteinuria, β2 microglobulin, phosphate, albumin and LVH were significantly correlated with circulating FGF21 levels after adjustment for BMI, gender age and diabetes mellitus in all CKD subjects." (PMID 21525989, 2011). "BMI, baseline ALT and triglyceride (TG) levels differed significantly between the normal and abnormal ALT groups, while age, sex, diabetes status, and the baseline cholesterol, bilirubin, albumin, and HBV DNA levels did not." (PMID 22087160, 2011). "Patients with diabetes must be tested for microalbuminuria (albumin to creatinine ratio 30–300 mg/mg), a range not detected using conventional urine dipsticks." (PMID 21860787, 2011). "Diabetes after 2 months resulted in a significant increase in the levels of immunoreactive albumin in the nonvascular retina (i.e., between vessels) in each of the four retinal layers studied." (PMID 22171162, 2011). "After adjusting for age, TC, hypertension, diabetes, body mass index, cigarette smoking, and alcohol consumption, the multivariate odds ratios (OR) of impaired ADL was highest among women in the lowest albumin quartile (≤4.0 g/dl)." (PMID 20571251, 2010). "On univariate analyses, in diabetes kallistatin concentrations correlated significantly with cystatin C, r = 0.28; p = 0.004, calculated GFR, r = -0.25; p = 0.009, urinary albumin/creatinine ratio, r = 0.34; p = 0.001, serum creatinine, r = 0.23; p = 0.01 and serum urea, r = 0.33, p = 0.001." (PMID 20860825, 2010). "One hundred patients (59 males and 41 females) with type-2 diabetes mellitus of duration six months or more and negative for albumin in urine by albustic method were included in the study." (PMID 20368924, 2009). "Covariates not retained in this backward selection included: age, diabetes mellitus, systolic blood pressure, Chlamydia pneumoniae (Cp) antibody titers, percent body fat, and urinary albumin/creatinine ratio." (PMID 19161617, 2009). "The exclusion of children with diabetes, kidney disease, or high γ-GT at baseline was done a priori, without knowledge of their albumin levels." (PMID 18335109, 2008). "The albumin to creatinine ratios were not increased in PodoTrsp-/- versus control mice after 3 or 6 months of diabetes, and in fact were similar to the levels seen in non-diabetic mice." (PMID 18647412, 2008). "Preoperative baseline data included age, gender, body mass index, total protein (TP), albumin (ALB), hemoglobin (HB), red blood cell count (RBC), white blood cell count (WBC), total lymphocyte count (TLC), platelet count (PLT), and the presence of diabetes or hypertension." (PMID 42317518, 2026). "Furthermore, CKD and malignancies were more prevalent in patients with lower albumin levels, while rates for arterial hypertension and diabetes mellitus did not significantly differ across the analysed subgroups." (PMID 41452958, 2026). "The sex, presence of diabetes mellitus (DM), hypertension (HTN), coronary artery disease (CAD), albumin, urea clearance index (Kt/V (D)), and high-sensitivity C-reactive protein (hs-CRP) levels were similar between the high and low groups for all metabolites." (PMID 41226502, 2025). "In addition to treatment, patient characteristics such as age, presence of diabetes, serum albumin, BMI class, and neutrophil/lymphocyte ratio (NLR) were not different between the 2 groups." (PMID 40231659, 2025). "The CaHMB ONS group showed a higher likelihood of increased muscle mass compared to the Diabetes-Specific ONS, with an odds ratio (OR) of 9.31 (95%CI: 2.16–40.13) for thickness and 3.96 (95%CI: 1.11–14.13) for area, adjusted for gender, age, serum albumin, and baseline glycated hemoglobin." (PMID 41156461, 2025).
diabetes (continued). "Glycated albumin levels tend to be higher in people with diabetes than in those without." (PMID 40863134, 2025). "Due to the shortened half-life of albumin in circulation, which is in substantial quantity lost in PD effluent, PD patients with diabetes exhibit low GA concentrations for their plasma glycemic level compared with non-PD patients with diabetes." (PMID 40430224, 2025). "Furthermore, among women categorized by normal BMD and those with osteopenia, significant differences were observed in age, height, weight, hypertension, diabetes, ALT, ALB, ALP, UA, BUN, TC, and HDL-C, with all differences also achieving statistical significance (P < .05)." (PMID 40859517, 2025). "Moreover, the association between albumin and the risk of PAD in patients with diabetes was not statistically different (P > 0.005)." (PMID 38405142, 2024). "Diabetic kidney disease (DKD), an insidious complication of diabetes mellitus (DM), is characterized by renal impairment or a glomerular filtration rate (GFR) < 60 ml/min/1.73 m2 and/or elevated urinary albumin excretion for at least 3 months." (PMID 38512446, 2024). "Although diabetes does not result in dramatic albuminuria in this model, silencing APOC3 prevented the increase in urinary albumin excretion associated with diabetes, suggesting that the improvement observed with APOC3 ASO is not due to an improvement in glycemia." (PMID 38743496, 2024). "Compared to non-gallstones participants, gallstone participants were more likely to be older, female, predominantly other Hispanic, smokers, non-drinkers, and to have diabetes, hypertension, higher BMI, higher albumin levels, higher neutrophil counts, and higher lymphocyte counts." (PMID 39758317, 2024). "Moreover, urinary albumin excretion predicted BP progression in individuals without diabetes and without hypertension." (PMID 38586159, 2024). "We found that patients with higher LDH levels were older, less female, more smoking, more often with diabetes, and appeared to arise with bigger hematoma volume and lower GCS score, more often with intraventricular hematoma, higher leukocytes, higher neutrocyte, lower lymphocyte, and lower albumin." (PMID 38404841, 2024). "Intriguingly, the cibersort score of DDCs in CD-PC was significantly lower than that of DKD group in the same hyperglycemic diabetes mellitus (DM) group, whose urinary albumin-to-creatinine ratio (UACR) did not meet the DKD standard, while the HDCs of CD-PC showed the opposite trend." (PMID 37686311, 2023). "Patients who died were older, had a higher proportion of diabetes, tumor size ≥5 cm, AFP ≥ 400 ng/mL, higher total bilirubin (TBIL), γ-glutamyl transferase (GGT), creatinine (Cr), and international prothrombin ratio (INR), and lower albumin levels (allp < 0.001) than those who survived." (PMID 37215223, 2023). "An animal model study showed the similar findings that the supplementation of exogenous C-peptide could reduce the urinary albumin excretion and inhibit the upregulation of type IV collagen via interaction with the TGF-beta signal in glomerular podocytes in mouses with type 1 diabetes mellitus." (PMID 37033221, 2023). "In females with diabetes (compared with females without diabetes), the decreased level of E2 may reduce creatinine clearance and increase urine albumin excretion and tubular fibrosis in the kidney, which may increase the risk of developing renal complications." (PMID 37143724, 2023). "Furthermore, albumin levels did not significantly correlate with the medical history variables analyzed, such as diabetes or hypertension." (PMID 38021540, 2023). "Therefore, attention should be given to dietary intake and screening of urinary albumin in individuals with high levels of circulating TFAs, particularly those with hypertension and those without diabetes." (PMID 37710270, 2023).